FGL2 (fibrinogen like 2)
Diseases named in the same sentence as FGL2 in open-access papers (continued):
Sharing a sentence is not in itself a finding about the gene and the disease.
esophageal cancer (3 papers, 2020 to 2022). A primary or metastatic malignant neoplasm involving the esophagus. "Fibrinogen-like protein 2 (FGL2), an immunosuppressive factor in the tumor microenvironment of various cancers, was upregulated in M2 macrophages, and higher FGL2 expression was associated with poorer survival in esophageal carcinoma patients." (PMID 33323552, 2020). "Thus, by secreting FGL2, M2-like tumor-associated macrophages may create an immunosuppressive tumor microenvironment that induces the occurrence and progression of esophageal carcinoma." (PMID 33323552, 2020). "Overexpression of FGL2 can predict worse survival in esophageal carcinoma." (PMID 35860577, 2022). "FGL2 expression level in esophageal cancer tissues was higher than normal tissues." (PMID 33323552, 2020). "Thus, we evaluated FGL2 expression in esophageal cancer tissues from TCGA and esophageal cancer cell lines from the Cancer Cell Line Encyclopedia database." (PMID 33323552, 2020). "However, FGL2 expression was low in esophageal cancer cell lines." (PMID 33323552, 2020). "Based on our findings, we analyzed the correlation of FGL2 expression with the prognosis of ESCA patients and the levels of tumor-infiltrating immune cells (TIICs) and cytokines in the esophageal cancer microenvironment." (PMID 33323552, 2020). "To better understand whether FGL2 is a crucial determinant of the TME and tumor metastasis in esophageal cancer, we compared the cytokine levels among EC109/9706 (ESCC) cells cultured alone, co-cultured with M0 macrophages or co-cultured with M2 macrophages." (PMID 33323552, 2020). "The correlation between the expression of FGL2 and the presence of specific infiltrating immune cells in ESCA suggested that FGL2 is a vital contributor to immune escape and immunosuppression in the esophageal cancer microenvironment." (PMID 33323552, 2020). "Using the TIMER database, we found that FGL2 expression correlated positively with the levels of immune markers of infiltrating B cells, CD8+ T cells, CD4+ T cells, macrophages, neutrophils and dendritic cells in esophageal carcinoma samples." (PMID 33323552, 2020).
liver cancer (3 papers, 2020 to 2024). An epithelial or non-epithelial malignant neoplasm that arises from the liver. "Multiple studies have demonstrated that FGL2 is highly expressed in liver cancer tissues and plays a crucial role in tumor progression by activating specific signaling pathways and modulating immune cell functions." (PMID 38816776, 2024). "The results of Liu indicated that knocking out FGL2 expression can significantly inhibit the growth of liver implant tumors and slow down the progression of liver cancer." (PMID 35136014, 2022). "Moreover, in the mouse models of liver cancer, CYP2E1 inhibitors not only reduced the incidence and size of tumors but also significantly decreased the expression of FGL2." (PMID 35136014, 2022).
liver fibrosis (3 papers, 2021 to 2024). "FGL2, a multifunctional protein, plays a role in promoting liver fibrin deposition and accelerating liver fibrosis, while also suppressing the immune system’s ability to clear the virus, leading to disease progression." (PMID 38816776, 2024). "Similarly, FGL2 has been reported to promote the progression of liver fibrosis by regulating the polarization state of macrophages." (PMID 39629005, 2024).
lymphoma (3 papers, 2014 to 2021). A malignant (clonal) proliferation of B- lymphocytes or T- lymphocytes which involves the lymph nodes, bone marrow and/or extranodal sites. "Overall, the increase in FGL-2 activity over a cutoff value of 150% appeared to exhibit a sensitivity of 73.6% and specificity of 80.7% for the diagnosis of lymphoma." (PMID 25303152, 2014). "It is intriguing to assume that increased activity of FGL-2 may have a role in lymphoma." (PMID 25303152, 2014). "Moreover, the observation that a significant decrease in FGL-2 activity was measured during remission of lymphoma may suggest that monitoring of FGL-2 activity may indicate the response to treatment." (PMID 25303152, 2014). "The FGL-2 activity in PBMC of this cohort of patients was similar to that observed in healthy controls (Mean ± SEM, 99%±27.9%; Median, 94%; p-value versus healthy controls = 0.97, p-value versus lymphoma patients <0.001)." (PMID 25303152, 2014). "In contrast to the increase in FGL-2 activity in PBMC of lymphoma patients, no increase in either mRNA or protein levels was observed." (PMID 25303152, 2014).
prostate carcinoma (3 papers, 2021 to 2024). A carcinoma that arises from epithelial cells of the prostate gland. "Recombinant FGL2 was overexpressed in a prostate carcinoma cell line (PC3)." (PMID 37200306, 2023). "For instance, we have shown that knockdown of FGL2 in a prostate carcinoma cell line reduced subcutaneous xenograft tumor growth and angiogenesis in a SCID mice model via the involvement of FGL2 in the MAPK signaling pathway." (PMID 37200306, 2023). "In the gene-array experiments using PC-3 (a wild type human prostate carcinoma cell line) clones, silencing FGL2 remarkable downregulates FGF-2, thus inhibiting the occurrence of prostate cancer in mice." (PMID 33867830, 2021).
acute hepatitis B (2 papers, 2018 to 2024). "The observation that sFGL2 levels are strongly elevated in acute hepatitis B patients compared to those in CHB supports previous in vivo studies in mice showing that infection with MHV3 induces FGL2 expression." (PMID 30419833, 2018).
acute pancreatitis (2 papers, 2014 to 2017). An acute inflammatory process that leads to necrosis of the pancreatic parenchyma. "The present study was designed to examine fgl2 expression in patients with severe acute pancreatitis (SAP) and its correlation with disease progression." (PMID 24348769, 2014).
asthma (2 papers, 2022 to 2025). "In children with asthma, we found an FGL2-driven subnetwork for B cell proliferation and T cell activation associated with both PM2.5 and ozone exposure; a CLC- and CPA3-driven subnetwork for leukocyte differentiation associated with ozone; and a TNFRSF10C-driven subnetwork associated with PM2.5." (PMID 41430723, 2025).
chronic kidney disease (2 papers, 2022 to 2023). Impairment of the renal function secondary to chronic kidney damage persisting for three or more months. "Fibrinogen-like 2 (FGL2) was recently found to be associated with fibrosis in a mouse model of kidney damage and was proposed as a potential therapeutic target in chronic kidney disease (CKD)." (PMID 36671474, 2022). "In this study, we investigated the association of FGL2 gene expression with kidney function and longitudinal outcomes in two independent cohorts of patients with chronic kidney disease." (PMID 36671474, 2022). "FGL2 mRNA expression is elevated in chronic kidney disease (CKD), and higher FGL2 levels are associated with fibrosis and worse outcomes." (PMID 37853350, 2023). "Hitherto human data on FGL2 in chronic kidney disease are limited, and longitudinal studies are especially lacking." (PMID 36671474, 2022).
dilated cardiomyopathy (2 papers, 2021 to 2023). Cardiomyopathy which is characterized by dilation and contractile dysfunction of the left and right ventricles. "FGL2 deletion in mice hearts induced early death and dilated cardiomyopathy, while FGL2 depletion led to ventricular dilatation and remodeling, highlighting the importance of FGL2 in heart function." (PMID 37893006, 2023).
hepatitis C infection (2 papers, 2010 to 2023). "HMBG1 secretion from injured hepatocytes induced NLRP3 inflammasome activation in macrophages, and fibrinogen-like protein 2 (Fgl2), which was upregulated in liver tissues of cirrhotic patients with underlying hepatitis C infection, promoted M1 polarization." (PMID 38116017, 2023).
Hypertension (2 papers, 2019 to 2024). The presence of chronic increased pressure in the systemic arterial system. "Interestingly, previous studies have suggested that increased FGL2 transcription and circulating levels are associated with cardiovascular pathologies, including hypertension, whereby increased mechanical force on the vascular wall induces a remodelling response." (PMID 39062880, 2024).
Insulin resistance (2 papers, 2020 to 2026). Increased resistance towards insulin, that is, diminished effectiveness of insulin in reducing blood glucose levels. "Glucose tolerance test (GGT) and insulin tolerance test (ITT) demonstrated that insulin resistance could be improved when fgl2 was deficient." (PMID 32863955, 2020). "Circulating FGL2 positively correlated with glycemic indices, insulin resistance, lipid parameters, renal tubular injury markers (NGAL, KIM-1), inflammatory cytokines (TNF-α, IL-6), and fibrotic mediators (TGF-β1, CTGF)." (PMID 42161877, 2026). "In addition to its influence on inflammation, fgl2 disruption also reduced weight gain, attenuated liver steatosis and insulin resistance in HFD- but not MCD-fed NASH mice." (PMID 32863955, 2020).
intracerebral hemorrhage (2 papers, 2021 to 2023). A cerebrovascular disorder characterized by bleeding into one or both cerebral hemispheres including the basal ganglia and the cerebral cortex. "BBB dysfunction has been reported as an early feature of many FGL2-related neuroinflammatory diseases, including traumatic brain injury and intracerebral hemorrhage." (PMID 37051251, 2023). "There is still a lack of effective treatments in offspring, as well as other FGL2-related neuroinflammatory diseases such as ischemic-reperfusion injury and intracerebral hemorrhage." (PMID 37051251, 2023).
lipid metabolism disorders (2 papers, 2020 to 2025). "Given the concurrent changes in proinflammatory cytokines, ROS and lipid metabolism upon fgl2 disruption, we hypothesize that fgl2 may cause lipid metabolism disorders in the liver through the induction of proinflammatory cytokines and ROS in macrophages." (PMID 32863955, 2020). "Together, these data demonstrated that fgl2 promoted LPS/FFA-triggered macrophages to produce inflammatory cytokines, which further induced lipid metabolism disorder in hepatocytes." (PMID 32863955, 2020). "We found that fgl2 interacted with TLR4 on macrophages and regulated inflammatory signaling pathways and the Nod-like receptor protein 3 (NLRP3) inflammasome, leading to liver damage and lipid metabolism disorders in the progression of NASH." (PMID 32863955, 2020). "Furthermore, we discovered that fgl2 combined with TLR4 mediates the activation of the Myd88-dependent signaling pathway, which may contribute to inflammation and lipid metabolism disorders." (PMID 32863955, 2020).
liver cirrhosis (2 papers, 2020 to 2025). "Fibrinogen-like protein 2 (FGL2), a ligand for FcγRIIb, was reported to be increased in patients with non-alcoholic fatty liver disease (NAFLD) and liver cirrhosis." (PMID 32093173, 2020).
lymphopenia (2 papers, 2025). Reduction in the number of lymphocytes. "Furthermore, plasma Fgl2 levels in COVID‐19 patients were positively correlated with CD8+ T‐cell lymphopenia." (PMID 41146434, 2025).
meningioma (2 papers, 2020 to 2022). A generally slow growing tumor attached to the dura mater. "Ten biomarkers, particularly AHCYL2, FGL2, and KCNMA1, were significantly related to grades and prognosis of meningioma." (PMID 32596316, 2020). "Though there were only four normal samples in GSE43290, the efficacy evaluation results still showed that five genes, including AHCYL2 (AUC = 0.729), FGL2 (AUC = 0.782), ID3 (AUC = 0.926), KCNMA1 (AUC = 0.745), and NMNAT2 (AUC = 0.851), could significantly distinguish meningiomas and normal samples." (PMID 32596316, 2020).
nonalcoholic steatohepatitis (2 papers, 2020 to 2021). "In this study, we sought to investigate the role of fgl2 in the pathogenesis of nonalcoholic steatohepatitis (NASH)." (PMID 32863955, 2020).
pancreatitis (2 papers, 2017 to 2024). Inflammation of the pancreas. "The present study aimed to explore the therapeutic effect of an adenovirus-mediated artificial miRNA targetting FGL2 (Ad-FGL2-miRNA) in taurocholate-induced murine pancreatitis models." (PMID 29054965, 2017).
rheumatoid arthritis (2 papers, 2014 to 2015). A chronic, systemic autoimmune disorder characterized by inflammation in the synovial membranes and articular surfaces. "Proteins not previously reported to be associated with rheumatoid arthritis including, coronin-1A (CORO1A), fibrinogen like-2 (FGL2), and macrophage capping protein (CAPG) were found to be upregulated in rheumatoid arthritis." (PMID 24393543, 2014).
severe acute respiratory syndrome (2 papers, 2013 to 2020). A viral respiratory infection caused by the SARS coronavirus. "Several disorders, including severe acute respiratory syndrome (SARS), abortion and allograft rejection, are correlated with FGL2." (PMID 32206449, 2020). "We and others have shown that FGL2 contributes to the pathogenesis of a number of experimental and human infectious diseases including mouse hepatitis virus strain 3 infection (MHV-3), severe acute respiratory syndrome (SARS), HIV infection and HBV and HCV infection." (PMID 24146739, 2013).
type 2 diabetes (2 papers, 2011 to 2014). "In a previous study, our group demonstrated that rat fgl2 is highly expressed in association with microthrombosis in rat type 2 diabetes and cardiac ischemia/reperfusion models." (PMID 24728278, 2014). "Enzyme linked immunosorbent assays (ELISA) additionally showed that circulating TNF-α levels in rats with type 2 diabetes were significantly elevated and closely correlated with fgl2 expression (r = 0.871, P < 0.01)." (PMID 23554679, 2011). "Based on the previous studies and our results, we concluded that TNF-α promoted fgl2 expression in glomerular and tubulointerstitial endothelial cells of rats with type 2 diabetes." (PMID 23554679, 2011). "In our study, levels of TNF-α in rats with type 2 diabetes were significantly elevated and were closely related to fgl2 expression." (PMID 23554679, 2011). "Microthrombosis due to fgl2 contributed to some extent to renal impairment of rats with type 2 diabetes." (PMID 23554679, 2011). "In rats with type 2 diabetes, fgl2 was found to be highly expressed in renal capillaries, which led to renal microthrombosis and the expression was associated with TNF-α." (PMID 23554679, 2011). "Our results showed that fgl2 and consequent hyaline microthrombosis were observed at renal microvessels in diabetic rats, which suggests that fgl2 may play a role in renal microangiopathy of rats with type 2 diabetes." (PMID 23554679, 2011). "Moreover, proinflammatory cytokines, such as TNF-α, could promote the expression of fgl2 in renal capillaries of rats with type 2 diabetes." (PMID 23554679, 2011).
alcoholic hepatitis (1 paper, 2024). Acute hepatitis resulting from ingestion of alcohol. "In cases of alcoholic hepatitis, FGL2 levels rise in liver macrophages, interacting with PKM2 to enhance glycolysis in proinflammatory macrophages and exacerbate liver damage." (PMID 38816776, 2024). "Recent research has shown that FGL2 plays a role in various liver-related conditions such as Autoimmune hepatitis (AIH), DILI, alcoholic hepatitis, liver parasitic infection, and liver ischemia-reperfusion injury." (PMID 38816776, 2024).
Alzheimer disease (1 paper, 2025). A progressive, neurodegenerative disease characterized by loss of function and death of nerve cells in several areas of the brain leading to loss of cognitive function such as memory and language. "The FGL2 locus may serve as a therapeutic target in efforts to mitigate amyloid pathology in Alzheimer’s disease." (PMID 40863490, 2025).
Aortic dissection (1 paper, 2023). Aortic dissection refers to a tear in the intimal layer of the aorta causing a separation between the intima and the medial layers of the aorta. "SLC11A1 and FGL2 are differently expressed in aortic dissection and may be involved in immune-inflammatory responses." (PMID 36755239, 2023).
Autoimmunity (1 paper, 2015). The occurrence of an immune reaction against the organism's own cells or tissues. "This review will focus on discussing the role of Treg in alloimmunity and autoimmunity, with an emphasis on the Treg effector molecule FGL2." (PMID 26241231, 2015). "In conclusion, the FGL2–FcγRIIB pathway is a critical immunoregulatory pathway that is involved in alloimmunity, autoimmunity, chronic infections, and cancer." (PMID 26241231, 2015). "Moving forward, therapies based on modulation of the FGL2–FcγRIIB pathway hold promise for the treatment of a wide variety of conditions ranging from autoimmunity to cancer." (PMID 26241231, 2015).
bladder tumor (1 paper, 2024). "The results from the TIMER database also showed the expression of FGL2 in pan-carcinoma, indicating downregulated FGL2 expression in bladder tumor tissues." (PMID 38903931, 2024).
cardiac hypertrophy (1 paper, 2020). "As a main result we found that AGAT−/− mice exhibited altered gene expression related to energy metabolism (Fbp2, Ucp2), cardiac hypertrophy and fibrosis (Nppa, Ctgf), immune response (Fgl2), and the conduction system of the heart (Dsc2, Ehd4, Hcn2, Hcn4, Scn4a, Scn4b)." (PMID 32179820, 2020).
cardiac ischemia (1 paper, 2014). "Nevertheless, the anti-Pep2 antibodies possessed a stronger affinity to rat fgl2 and more intensive inhibition on rat fgl2 prothrombinase activity, as evidenced by cultured rat microvascular endothelial cells in vitro or rat cardiac ischemia/reperfusion model in vivo (unpublished data)." (PMID 24728278, 2014).
chronic hepatitis (1 paper, 2018). An active inflammatory process affecting the liver for more than six months. "In HCV infection, plasma FGL2 levels are extensively increased in patients with chronic hepatitis compared to healthy controls." (PMID 30419833, 2018).
colorectal tumors (1 paper, 2024). "The T cell population in pancreatic and colorectal tumors also exhibits Cd8+Fgl2+Il2rb+ cells, similar to tolerant allografts." (PMID 38888968, 2024). "Interestingly, upon analysis of single-cell RNA-seq (scRNA-seq) data from pancreatic and colorectal tumors in mice, we have identified similar cells within the CD8+ T cell cluster that express Fgl2 and Il2rb (CD122)." (PMID 38888968, 2024).
cutaneous squamous cell carcinoma (1 paper, 2022). "However, there is little research on the role of Fgl2 in cutaneous squamous cell carcinoma (CSCC) growth." (PMID 34975313, 2022).
gastrointestinal stromal tumor (1 paper, 2024). "proved that high expression of FGL2 in gastrointestinal stromal tumors was associated with favorable survival outcomes with better recurrence-free survival, small size, and low tumor-infiltrating lymphocytes." (PMID 39575432, 2024).
glomerulonephritis (1 paper, 2013). A renal disorder characterized by damage in the glomeruli. "Consistent with this, targeted deletion of fgl2 leads to impaired Treg activity and enhanced reactivity of DC, T and B cells and autoimmune kidney disease (glomerulonephritis)." (PMID 24146739, 2013).
hypercoagulable (1 paper, 2020). "Our finding of a differential upregulation of FGL2 suggests that FGL2 with or without HRG may be a major risk factor for a hypercoagulable state induced by a high-salt diet and may be a potential drug target for clinical treatment of cardiovascular disease induced by a high-salt diet." (PMID 33250683, 2020).
ischemia (1 paper, 2005). A hypoperfusion of the BLOOD through an organ or tissue caused by a PATHOLOGIC CONSTRICTION or obstruction of its BLOOD VESSELS, or an absence of BLOOD CIRCULATION. "These cytokine levels correlated with strong expression of fgl2 prothrombinasein decidua as well as in trophoblast suggesting a maternal vascular etiology with thrombosis and ischemia." (PMID 16092971, 2005).
kidney damage (1 paper, 2022). "Increased soluble FGL2 in kidney tissue might be the expression of an insufficient compensatory mechanism in response to kidney damage." (PMID 36671474, 2022).